TEK (TEK receptor tyrosine kinase)
Diseases named in the same sentence as TEK in open-access papers (continued):
Sharing a sentence is not in itself a finding about the gene and the disease.
Obesity (7 papers, 2017 to 2024). Accumulation of substantial excess body fat. "Among these loci were MC4R (melanocortin-4 receptor), an obesity-associated gene, and TEK (TEK receptor tyrosine kinase, rs78411354), which plays a role in embryonic vascular development." (PMID 36240095, 2022).
ocular hypertension (6 papers, 2016 to 2024). Abnormally high intraocular pressure. "Intriguingly, recent GWAS studies of subjects with ocular hypertension have identified common variants in members of the Angpt-TEK signaling pathway." (PMID 31621585, 2019). "Compared to Tek haploinsufficient mice, which exhibit elevated IOP and loss of retinal ganglion cells, Tek+/-;Ptprb+/- mice have elevated TEK phosphorylation, which allows normal SC development and prevents ocular hypertension and RGC loss." (PMID 31621585, 2019). "Furthermore, in Tek+/- haploinsufficient mice, this increased TEK activation is sufficient for normal SC development, preventing both ocular hypertension and retinal ganglion cell (RGC) loss." (PMID 31621585, 2019). "ANGPT2-clustering antibody treatment was found to increase TEK phosphorylation in aged mice and lower IOP in an injury-induced model of ocular hypertension." (PMID 31621585, 2019).
renal cell carcinoma (6 papers, 2013 to 2024). "Vascular endothelial growth factor C (VEGF-C), interleukin-4 (IL-4), colony-stimulating factor 2 (CSF2), prospero homeobox 1 (PROX1), and TEK receptor Tyrosine Kinase (TEK) is significantly associated with lymph node metastasis in renal cell carcinoma (RCC)." (PMID 38167072, 2024).
lung diseases (5 papers, 2010 to 2025). "There was some evidence that EDNRB, RXFP1, ANGPT1, and TEK are closely related to lung diseases and cancer." (PMID 34039311, 2021).
renal carcinoma (5 papers, 2013 to 2025). A carcinoma arising from the epithelium of the renal parenchyma or the renal pelvis. "We next investigated whether shikonin and acetylshikonin regulate TEK expression in renal cancer cell lines." (PMID 40808675, 2025). "It is worth mentioning that previous studies have found that TEK knockdown can significantly promote AKT phosphorylation and inhibit the apoptosis of renal cancer cells by upregulating the downstream pro-apoptotic proteins Bcl-2 and Bcl-xL." (PMID 40808675, 2025).
non-small cell lung carcinoma (4 papers, 2016 to 2024). A group of at least three distinct histological types of lung cancer, including non-small cell squamous cell carcinoma, adenocarcinoma, and large cell carcinoma. "A previous study showed that normal lung tissues expressed constitutively high and correlated levels of ANGPT1 and TEK, which were significantly reduced in non-small cell lung cancers (NSCLC)." (PMID 34039311, 2021). "However, clinical studies have demonstrated downregulation of ANGPT1 and TEK expression levels in non-small-cell lung cancer (NSCLC) tissue." (PMID 39595659, 2024).
oral squamous cell carcinoma (4 papers, 2020 to 2022). "Oral squamous cell carcinoma: three patients showed moderate expression (30%), four patients showed weak expression (40%), and three patients showed no expression of TEK (30%)." (PMID 32437034, 2020).
allergic conjunctivitis (3 papers, 2020 to 2025). "In the stage I association study of allergic conjunctivitis, we selected 5 SNP in the TEK gene with nominally significant p-values." (PMID 32180797, 2020). "In stage I, 112 SNPs were screened in the TEK gene of the patients in order to search for associations with asthma and allergic conjunctivitis." (PMID 32180797, 2020). "We screened an allergic population (discovery cohort) with 112 SNPs in the TEK gene and searched for associations with asthma and allergic conjunctivitis." (PMID 32180797, 2020). "In the present study, we investigated whether genetic variations in the TEK gene influence the susceptibility to asthma or allergic conjunctivitis in multiple populations." (PMID 32180797, 2020). "It was suggested that variations in the TEK gene might influence the susceptibility to asthma and allergic conjunctivitis." (PMID 32180797, 2020). "In the present study, we aimed to further investigate the possible role of the TEK gene in asthma and allergic conjunctivitis involving novel populations." (PMID 32180797, 2020). "In conclusion, our results provide additional proof that the Tie2 pathway, the TEK gene and its variations might have a role in asthma and allergic conjunctivitis." (PMID 32180797, 2020). "TEK is abundantly expressed in the lung and in the endothelium of Schlemm’s canal in the eye and the Tie2 pathway has been suggested that it might play a role in asthma and different eye disorders including allergic conjunctivitis." (PMID 32180797, 2020).
asthma (3 papers, 2020 to 2025). "The role of variations in the TEK gene in human asthma was first suggested by a meta-analysis of genome-wide association studies, that identified four SNPs on chromosome 9p21.2 associated with asthma in a European American population." (PMID 32180797, 2020). "Earlier, we investigated in a pediatric European population whether three expression QTL SNPs in the TEK gene influenced the susceptibility to asthma or associated phenotypes." (PMID 32180797, 2020). "Based on its function, it has been hypothesized that variations in the TEK gene were responsible for the association with asthma." (PMID 32180797, 2020). "We think, however, that the collected proofs that the TEK gene and its variations might have a role in asthma are quite convincing." (PMID 32180797, 2020). "Later, an association study investigating three eQTL SNPs in the TEK gene with known respiratory disease association found no connection with asthma." (PMID 32180797, 2020). "The functions of the Tie2, the results of the gene expression in the animal model and the association studies in independent populations strengthen each other, providing accumulating evidence that TEK is a potential gene in asthma pathogenesis." (PMID 32180797, 2020).
head and neck squamous cell carcinoma (3 papers, 2020 to 2025). A squamous cell carcinoma that arises from any of the following anatomic sites: lip and oral cavity, nasal cavity, paranasal sinuses, pharynx, larynx, and salivary glands. "Polymorphic variants of TEK gene c.1521A > G (rs639225) GA/AA were associated with unfavorable OS of head and neck squamous cell carcinoma either among all patients, or in patients treated with the combination treatment (radiotherapy and cisplatin-based chemotherapy)." (PMID 34209679, 2021). "The genotypes ANGPT2 (rs3739391) GA/AA, ANGPT2 (rs3020221) CC, TEK (rs639225) GA/AA, and VEGF (rs2010963) CC was related to decreased OS in patients with head and neck squamous cell carcinoma treated with the combination therapy." (PMID 34209679, 2021). "Here, we have explored the crucial role of Tunica Interna Endothelial Cell Kinase (Tie2/TEK) signaling in transition and maintenance of myofibroblastic phenotype of CAFs, and as possible link with the poor prognosis of head and neck squamous cell carcinoma (HNSCC) patients." (PMID 40349056, 2025).
astrocytoma (2 papers, 2010 to 2022). "Except for CCND2, FLT1, FOXC2, KDR, KRT14, and TEK, the mRNA expression ratio of cancer pathway-associated genes in the astrocytoma grade III cell line (SW1088) was comparable to that of other tumour cell lines." (PMID 36142793, 2022). "The genes CDH2, DDB2, DSP, EPO, FGF2, and TEK were overexpressed in an astrocytoma cell line." (PMID 36142793, 2022). "The tyrosine kinase receptor Tie2/TEK was initially reported as a specific vascular receptor present in both normal and tumoral endothelial cells (EC), including ECs in astrocytomas, and its levels correlate positively with increasing malignancy." (PMID 21321379, 2010).
Cirrhosis (2 papers, 2022 to 2025). A chronic disorder of the liver in which liver tissue becomes scarred and is partially replaced by regenerative nodules and fibrotic tissue resulting in loss of liver function. "We use the bioinformatical analysis to verify that AKR1C3, NQO1, TEK, and TPX2 have good diagnostic performance in patients with cirrhosis." (PMID 36686655, 2022). "A violin plot shows that the expression of AKR1C3, NQO1, TEK and TPX2 was significantly associated with different disease states (normal, cirrhosis or liver cancer) (p < .05) (GSE54238)." (PMID 36686655, 2022). "The AUCs of expression of AKR1C3, NQO1, TEK, and TPX2 between cirrhosis and HCC were .9.74.77, and .89, proving that the four target genes have predictive value." (PMID 36686655, 2022). "In this regard, increased plasma concentrations of several angiogenic mediators, including angiopoietin 2, TEK tyrosine kinase endothelial (Tie2), intercellular adhesion molecule 3 (ICAM3), and vascular cell adhesion molecule 1 (VCAM1), are increased in patients with HPS and cirrhosis." (PMID 40171298, 2025).
lung adenocarcinoma (2 papers, 2021 to 2024). A carcinoma that arises from the lung and is characterized by the presence of malignant glandular epithelial cells. "Overall, these findings suggest that circRNAs regulate TEK signaling in lung adenocarcinoma and may serve as potential therapeutic targets for this disease." (PMID 38200584, 2024). "Our bioinformatic analysis identified six downregulated DEGs (EDNRB, RXFP1, P2RY1, CALCRL, TEK, and ANGPT1) between lung adenocarcinoma and normal lung tissues based on two different microarray datasets." (PMID 34039311, 2021).
lymph node metastasis (2 papers, 2015 to 2025). "Our findings indicate that lower TEK expression correlates with advanced tumor stage, lymph node metastasis, higher histological grade, distant metastasis, and advanced clinical stage in RCC." (PMID 40808675, 2025). "Five genes (VEGFA, IFNB1, IGF1, TEK, and TGFBR1) are associated with angiogenesis, which provides clues to the mechanism of the association between epigenetic inactivation of CYB5R2 and lymph node metastasis." (PMID 26275421, 2015).
abdominal aortic aneurysm (1 paper, 2021). Enlargement and ballooning of the vessel that supplies arterial blood to the abdomen, pelvis and legs. "TEK is inactivated during the process of angiogenesis and inflammation, which leads to neovascularization of the abdominal aortic aneurysm and increased infiltration of monocytes/macrophages." (PMID 34080122, 2021).
aneurysm (1 paper, 2021). Bulging or ballooning in an area of an artery secondary to arterial wall weakening. "Increased expression of TEK was observed in cell lines obtained from the inner layers of aneurysm compared to the standard HAEC line." (PMID 34080122, 2021).
central serous chorioretinopathy (1 paper, 2023). "In humans, polypoidal choroidal vasculopathy-associated variants are found in ANGPT2 and TEK, and additional variants related to central serous chorioretinopathy are identified in PTPRB, which encodes phosphatase dephosphorylating TEK." (PMID 36982446, 2023).
chronic obstructive pulmonary disease (1 paper, 2015). A chronic and progressive lung disorder characterized by the loss of elasticity of the bronchial tree and the air sacs, destruction of the air sacs wall, thickening of the bronchial wall, and mucous accumulation in the bronchial tree. "TEK has been shown to be down-regulated among smokers and individuals with chronic obstructive pulmonary disease." (PMID 26230583, 2015).
Corneal opacity (1 paper, 2024). A reduction of corneal clarity. "Similarly, it is reported that mutations in the PXDN gene cause corneal opacity and CG and that mutations in the TEK gene likely underlie CG." (PMID 39158757, 2024).
leukoplakia (1 paper, 2020). A white patch or plaque on a mucous membrane that cannot be characterized clinically or pathologically as any other disease. "TEK expression in healthy tissue did neither significantly differ in comparison to normal mucosa (P =.595) nor to leukoplakia (P =.057)." (PMID 32437034, 2020).
medulloblastoma (1 paper, 2015). A malignant, invasive embryonal neoplasm arising from the cerebellum. "When hAT-MSCs were co-cultured with medulloblastoma-BTICs, the expression levels of CCR4, CCR5, CCR7, XCR1, CXCR1, CXCR4, PDGFR-bb, KDR and TEK were increased, while the levels of CX3CR1, IL1R, IL6R, IL8R, IGF1R and CD44 were decreased (p<0.05)." (PMID 26076490, 2015).
Mucocutaneous venous malformations (1 paper, 2025). Mucocutaneous venous malformations (VMCMs) are hereditary vascular malformations characterized by the presence of small, multifocal, bluish-purple venous lesions involving the skin and mucosa. "Germline TEK mutations have been reported to cause a rare, inherited form of venous anomaly known as mucocutaneous venous malformation." (PMID 41153341, 2025).
myeloid leukemia (1 paper, 2021). A clonal proliferation of myeloid cells and their precursors in the bone marrow, peripheral blood, and spleen. "Alongside the VEGF family, the Angiopoietins (Ang-1, Ang-2) and their shared receptor (Tie2/TEK) are the most specific inducers of angiogenesis dysregulated in myeloid leukemia." (PMID 33777944, 2021).
Noonan syndrome (1 paper, 2023). Noonan Syndrome (NS) is characterized by short stature, typical facial dysmorphism and congenital heart defects. "In one patient, in addition to the somatic TEK mutation found in VA biopsy, a germline PTPN11 mutation causing Noonan syndrome was detected." (PMID 37380669, 2023).
Ovarian cyst (1 paper, 2020). The presence of one or more cysts of the ovary. "It should be noted that several members of family 8 shared additional nonocular clinical features, such as Perthes disease and ovarian cysts, which may also be related to abnormal SVEP1 and/or TEK signaling." (PMID 33027505, 2020).
pituitary tumor (1 paper, 2022). A benign or malignant neoplasm affecting the pituitary gland. "In contrast, expression of ANGPT2 (3.6 x 103 copies/μg total RNA) and TEK (3.4 x 103) was significantly elevated in all types of pituitary tumors with an overall increase of 9.2 (p<0.0001) and 7.3-fold (p<0.0001), respectively." (PMID 35600354, 2022).
thyroid (1 paper, 2025). "Integration with conventional DEG signatures revealed a functionally cohesive module, with C1QA/B/C, FLT1, TEK, PDGFRB, SPP1, and HLA-DPB1 emerging as central regulators of thyroid irAEs." (PMID 41221294, 2025).
tumor (550 papers, 1998 to 2026). "Low Tie2 expression, encoded by TEK, has been shown to increase vascular permeability, enhancing inflammatory cell migration and tumor angiogenesis." (PMID 40808675, 2025). "GO and KEGG analyses revealed that TEK expression was associated with critical structural and regulatory functions within the tumor microenvironment." (PMID 40808675, 2025). "The results indicated that lower TEK expression was significantly associated with advanced tumor stage (T3-T4), lymph node metastasis, higher histologic grade (G3-G4), distant metastasis, advanced clinical stage (Stage III-IV), and sarcomatoid component." (PMID 40808675, 2025). "In BCa, METTL3 regulates the PI3K/AKT pathway associated with tumor angiogenesis and promotes tumor angiogenesis by modulating TEK and VEGFA." (PMID 39295872, 2024). "In this study, we developed a novel angiogenesis score and feature genes (MMRN2, CLEC14A, ACVRL1, EFNB2, and TEK) which was associated with tumor angiogenesis microenvironment and prognosis in KIRC patients." (PMID 33761933, 2021). "This includes two tumors with two mutations: one tumor with both FLT1 and KDR mutations and one tumor with both TEK (TIE2) and KDR (VEGFR2) mutations." (PMID 33322802, 2020). "We aimed to search for mutations in the germline and somatic DNA of the TEK gene and to analyze the expression level of Src and phospho-Src (p-Src) in tumor and healthy tissues from patients with facial cutaneo-mucosal venous malformations (VMCM)." (PMID 28316284, 2017). "Furthermore, the elevated levels of VCAM1 and TEK in HCC patients suggest their role in tumor progression and potential as diagnostic markers." (PMID 39286634, 2024). "GSEA plots demonstrated significant enrichment of the “G2M checkpoint” and “MYC target pathways” in the high TEK expression group, linking TEK to cell cycle control and oncogenic transcriptional regulation, supporting its role as a tumor suppressor in RCC." (PMID 40808675, 2025). "In contrast, TEK showed upregulation across all tumor cell lines but only displayed statistical significance in the 786-O cell line (P < 0.01)." (PMID 40028163, 2025). "Collectively, these findings suggest that shikonin can exerts its anti-tumor effects by binding to and upregulating TEK, which subsequently suppresses the AKT/mTOR signaling pathway." (PMID 40808675, 2025). "Together, these findings underscore the potential tumor-suppressive role of TEK in RCC by affecting proliferation, migration, and invasion properties." (PMID 40808675, 2025). "Given the reduced ANGPTL1/TEK signaling in MDA-MB-231 VMT and clinical TNBC, which correlates with disrupted vasculature, our objective was to investigate the potential benefits of increasing TEK signaling in the tumor EC by blocking VE-PTP with razuprotafib." (PMID 38183074, 2024). "The hypermethylated pattern identified in the promoters of EC markers CD34, EMCN, and TEK suggests a downregulated expression in tumor tissues." (PMID 39103878, 2024). "M6A modification mediated by METTL3 is essential for the activation of tumor progression and angiogenesis mediated by TEK/VEGFA." (PMID 39295872, 2024). "Analysis of the five hypoxia- and immune-related genes also showed high expression of EPO, TGFB1, TGFA, and PLAUR, but low expression of TEK in tumor samples." (PMID 35222525, 2022). "TEK delays tumor growth, slows down metastasis, and enhances the response to accompanying cytotoxic therapy." (PMID 36686655, 2022). "Other studies have shown that TEK activation favorably changes TME and immune infiltration, polarizes tumor-associated macrophages (TAM) toward M1-like phenotypes and reduces regulatory T cell (Treg) infiltration." (PMID 33602230, 2021). "Taken together, Mettl3-mediated m6A modification is required for the activation of TEK–VEGF-A-mediated tumor progression and angiogenesis." (PMID 33681207, 2021).